CARM1 (coactivator associated arginine methyltransferase 1)
Diseases named in the same sentence as CARM1 in open-access papers (continued):
Sharing a sentence is not in itself a finding about the gene and the disease.
leukemia (7 papers, 2017 to 2024). A malignant (clonal) hematologic disorder, involving hematopoietic stem cells and characterized by the presence of primitive or atypical myeloid or lymphoid cells in the bone marrow and the blood. "It is also essential for AE9a-driven leukemia maintenance, as mice depleted for Carm1 show significant improvements in survival compared to wild types." (PMID 36358861, 2022). "CARM1 and Mi2 form a complex with the transcription factor c-Myb and regulate the c-Myb target gene’s transcription in several leukemia cell lines." (PMID 36358861, 2022). "The majority of 4a–n exhibited potent dual p300 and CARM1 inhibition, sometimes reaching the submicromolar level, and induction of apoptosis mainly in the tested leukemia cell lines." (PMID 32650558, 2020). "Mechanistically, genetic perturbation of CARM1 in the context of leukemia impairs cell-cycle progression, promotes myeloid differentiation, and ultimately induces apoptosis, probably by targeting pathways of proliferation and cell-cycle progression, that is, E2F-, MYC-, and mTOR-regulated processes." (PMID 31657716, 2019). "The knockdown of CARM1 induces myeloid differentiation of AML cell lines and reduces the leukemia burden in vivo." (PMID 36358861, 2022). "Indeed, Carm1-deficient mice failed to develop leukemia even one year after transplantation." (PMID 36358861, 2022). "We see important biological differences in the ability of phosphorylatable vs. non-phosphorylatable CARM1 to support leukemia cell proliferation and demonstrate the therapeutic relevance of targeting both JAK2-V617F and CARM1 in JAK2-V617F-positive cells." (PMID 38649367, 2024).
lung adenocarcinoma (7 papers, 2020 to 2025). A carcinoma that arises from the lung and is characterized by the presence of malignant glandular epithelial cells. "Meng, Chen, and Han research showed that PFKFB4 promotes the proliferation, migration, and invasion of lung adenocarcinoma (LUAD) cells by enhancing the phosphorylation of SRC‐2‐mediated CARM1 expression, offering a new perspective for LUAD treatment." (PMID 39964832, 2025). "To understand the precise molecular mechanism of PFKFB4-SRC-2-drived lung adenocarcinoma progression, we overexpressed CARM1 in si-SRC-2 #1-transfected LUAD cells, of which SRC-2 had been mostly knockdown." (PMID 33593309, 2021). "Phosphorylation of SRC-2 at S487 increased its transcriptional activity and upregulated CARM1 expression, thus promoting lung adenocarcinoma cells proliferation, migration and invasion." (PMID 33593309, 2021). "Moreover, the suppressed proliferation ability of PFKFB4 knockdown in lung adenocarcinoma cells was reversed upon overexpression of CARM1 in PFKFB4-knockdown A549 and NCI-H1975 cells." (PMID 33593309, 2021). "Our research reveal that PFKFB4 promotes lung adenocarcinoma cells proliferation, migration and invasion via enhancing phosphorylated SRC-2-mediated CARM1 expression." (PMID 33593309, 2021). "Taken together, these data showed that overexpression of CARM1 could abolish the suppressed effects induced by PFKFB4 knockdown, which suggested that PFKFB4 promoted lung adenocarcinoma cells proliferation through SCR-2/CARM1 axis." (PMID 33593309, 2021). "Furthermore, we identified that CARM1 was transcriptionally regulated by SRC-2 and involved in PFKFB4-SRC-2 axis on lung adenocarcinoma progression." (PMID 33593309, 2021).
pancreatic cancer (7 papers, 2020 to 2025). "Wang showed that methylation of MDH1 by CARM1 inhibited glutamine metabolism in pancreatic cancer cells." (PMID 37649137, 2023). "At the same time, they also observed that the expression of CARM1 in pancreatic cancer is significantly lower than in normal tissue, accompanied by the activation of MDH1, revealing the important role of CARM1 in regulating pancreatic cancer metabolism through MDH1 methylation." (PMID 39964832, 2025). "Paradoxically, CARM1 shows a tumor-inhibiting effect on liver and pancreatic cancers." (PMID 35246137, 2022). "However, CARM1 inhibits the progression of liver and pancreatic cancers." (PMID 35246137, 2022). "Carm1-mediated arginine methylation of MDH1 inhibits glutamine metabolism, thereby inhibiting the growth of pancreatic cancer." (PMID 36968582, 2023). "A recent study suggests that methylation on arginine 248 inhibits MDH1 catalytic activity and dimerization by coactivator-associated arginine methyltransferase 1 (CARM1), and KRAS suppresses CARM1-mediated MDH1 methylation, contributing to glutamine metabolism in pancreatic cancer." (PMID 33117704, 2020).
small cell lung carcinoma (7 papers, 2021 to 2026). Small cell lung cancer (SCLC) is a highly aggressive malignant neoplasm, accounting for 10-15% of lung cancer cases, characterized byrapid growth, and early metastasis. "We have shown that arginine methylation of NFIB is important for the progression of small cell lung cancer, and elimination of this methylation either by removal of CARM1 or by mutation of the NFIB methylation site, significantly prolongs the survival of the SCLC mouse model." (PMID 36690626, 2023). "In small cell lung cancer, the ratio of CARM1-FL to CARM1-ΔE15 correlates with differential responses to chemotherapy." (PMID 41152553, 2025). "This is line with the work of Mark Bedford’s group showing that CARM1 can promote an open chromatin state in small cell lung cancer models." (PMID 40321217, 2025). "employed a small cell lung cancer (SCLC) mouse model to investigate the crucial role of CARM1 methylation of NFIB in its transformational activity." (PMID 39964832, 2025). "Here the authors show that protein arginine methyltransferase, CARM1, methylates transcription factor NFIB to promote the growth of small cell lung cancers." (PMID 36690626, 2023).
triple-negative breast carcinoma (6 papers, 2021 to 2026). An invasive breast carcinoma which is negative for expression of estrogen receptor (ER), progesterone receptor (PR), and human epidermal growth factor receptor 2 (HER2). "It is worthwhile emphasizing that HIF1A also promotes the proliferation and invasion of triple-negative breast cancer (TNBC) by forming a complex with CARM1, which regulates the transcription of genes associated with hypoxic adaptation and tumor progression." (PMID 39995416, 2025). "This notion is further supported by findings that triple-negative breast cancer frequently overexpresses a cytoplasm-enriched splice variant, CARM1-ΔE1561." (PMID 41152553, 2025). "Arginine-methylation of BAF155 by coactivator-associated arginine methyltransferase 1 (CARM1) promotes triple-negative breast cancer (TNBC) metastasis." (PMID 34865122, 2021). "The function of CARM1 in triple-negative breast cancer (TNBC) is still unclear and requires further exploration." (PMID 38476024, 2024). "We found that CARM1 expression was elevated in triple-negative breast cancers." (PMID 38476024, 2024). "Moreover, the parallels to CARM1 biology strengthen the mechanistic plausibility: in triple-negative breast cancer, CARM1 promotes proliferation, epithelial–mesenchymal transition (EMT), and stemness, in part by interacting with β-catenin and influencing Wnt pathway targets." (PMID 41516402, 2026).
glioblastoma (5 papers, 2021 to 2025). The most malignant astrocytic tumor (WHO grade IV). "Additionally, Kappadakunnel's group found increased CARM1 expression in glioblastoma samples and associated changes in PRMT4 expression with poorer patient survival rates." (PMID 39964832, 2025). "Our work demonstrates that loss of CARM1 causes a reduction in GSC cell proliferation and gives support to the proposal that CARM1 should be further investigated as a therapeutic target in Glioblastoma, perhaps focusing on the stem-like population." (PMID 40321217, 2025). "CARM1 mRNA expression is also strongly correlated with glioblastoma patient survival, with lower CARM1 expression correlating with increased patient survival." (PMID 40321217, 2025). "We first wanted to understand the clinical impact of CARM1 in Glioblastoma, so we initially analyzed publicly available datasets from the TCGA." (PMID 40321217, 2025). "Our work set out to discover if CARM1 is a reasonable therapeutic target for Glioblastoma and how CARM1 regulates GSC character and developmental processes." (PMID 40321217, 2025). "Overall, our work provides novel insight on how CARM1 regulates cell fate commitment in GSCs and reveals a new therapeutic approach for the treatment of Glioblastoma." (PMID 40321217, 2025). "In summary, PRMT3 and CARM1 are viewed as potential oncogenes, their overexpression significantly impacting a variety of cancers, such as colorectal, liver, pancreatic, prostate, endometrial, breast, ovarian, oral cancers, and glioblastomas." (PMID 39964832, 2025). "The arginine methyltransferase, CARM1, has been shown to play critical roles in maintaining stem cell pluripotency, preventing differentiation, and recently was discovered to be upregulated in Glioblastoma." (PMID 40321217, 2025). "The results of biological function and overexpression of CARM1 presented here may indicate a new therapeutic target to attack human glioblastoma." (PMID 35274101, 2022). "Despite the gaps in knowledge that exist about radial glial cells in Glioblastoma, to our knowledge, we are the first group to reveal that CARM1 regulates the transcriptomic/proteomic radial glial lineage in GSCs and may shed new light on the fundamental characteristics of GSC plasticity." (PMID 40321217, 2025). "The aim of this study was to investigate the expression of four pluripotency-related genes (OCT4, NANOG, SOX2, and CARM1) in human glioblastoma (GBM)." (PMID 35274101, 2022). "The expression of four pluripotency-related genes was investigated (OCT4, NANOG, SOX2, and CARM1) in the most malignant primary human brain tumor, glioblastoma (GBM)." (PMID 35274101, 2022). "However, how CARM1 alters developmental signaling and cell fate in Glioblastoma remains unknown." (PMID 40321217, 2025). "The Myc/SWD3 complex is recruited to the PRMT4 (CARM1) promoter, and PRMT4 expression enhances glioblastoma proliferation." (PMID 36835628, 2023). "To date, there is little to no understanding of the role that CARM1 plays in regulating developmental processes in Glioblastoma." (PMID 40321217, 2025).
diabetic retinopathy (4 papers, 2015 to 2025). "Elevated CARM1 expression has been observed in type II diabetes, diabetic retinopathy, and obesity, with recent studies illuminating its crucial role in liver pathophysiology, lipid metabolism, and adipogenesis." (PMID 39922487, 2025). "Inhibitors such as 2,3,7,8-tetrahydroxy-benzopyranol[5,4,3-cde]benzopyran-5,10-dione (TBBD) and ellagic acid have shown promise in attenuating retinal pigment epithelium cell apoptosis during diabetic retinopathy progression by blocking CARM1 activity and H3R17 dimethylation." (PMID 39922487, 2025).
diffuse large B-cell lymphoma (4 papers, 2021 to 2025). "A more recent study showed that diffuse large B-cell lymphoma cells with genetic lesions in genes encoding CREB-binding protein and E1A-binding protein P300 are more sensitive to CARM1 inhibition." (PMID 40123976, 2025). "Inhibition of CARM1 activity slows diffuse large B-cell lymphoma (DLBCL) growth, which is positively correlated with CBP/P300-mutation status, indicating that the CBP/P300 mutation in cancer creates a vulnerability to targeting CARM1 activity." (PMID 34006904, 2021). "Inhibition of CARM1 can further decrease the HAT activity of CBP and the expression of target genes, leading to synthetic lethality in diffuse large B cell lymphoma (DLBCL) tumors with mutant CREBBP/EP300." (PMID 38619752, 2024).
glioma (4 papers, 2018 to 2025). A benign or malignant brain and spinal cord tumor that arises from glial cells (astrocytes, oligodendrocytes, ependymal cells). "It has also been suggested that CARM1 was considerably associated with multiple immune responses and infiltration, and immunotherapies along with CARM1 inhibitors may be an effective strategy to suppress the human ungracious tumors, mainly gliomas." (PMID 34745258, 2021). "We identified that CARM1 is significantly overexpressed in high grade glioma in comparison to low grade glioma, in line with previous findings." (PMID 40321217, 2025). "Since NFIA specifically has been shown to be significantly involved in Glioma tumorigenesis we hypothesized NFIA to be the primary CARM1 substrate responsible for regulating NGFR signaling in GSCs." (PMID 40321217, 2025). "CARM1 differential expression was seen in all gliomas with distinct clinical features, suggesting that CARM1 may play a role in cancer growth and progression." (PMID 34745258, 2021). "CARM1 has been reported to be involved in cell development and differentiation in various organ systems including the nervous system, but its role in developmental signaling in Glioma is still unknown." (PMID 40321217, 2025). "This suggest that in GSCs loss of CARM1 does not necessary lead to complete cell differentiation but instead leads to a shift in stem-like cell lineage promoting a more radial glial like cell type in Glioma." (PMID 40321217, 2025). "Since low CARM1 expression is associated with increased GBM patient survival and has been previously reported to slow cell growth in LN229 cells, we hypothesized that depletion of CARM1 would also slow proliferation of Glioma stem-like cells." (PMID 40321217, 2025). "As a model system, we used CRISPR/Cas9 along with a negative selection approach to ablate the CARM1 gene in CD133+ patient derived glioma stem-like cells (GSCs)." (PMID 40321217, 2025).
melanoma (4 papers, 2010 to 2024). A malignant, usually aggressive tumor composed of atypical, neoplastic melanocytes. "EP400, Mi-2β, PRDM4, NCOA6 or CARM1 silencing significantly induced the response to T-cell attack in melanoma cells, and led to more than 20% of the melanoma cells to be eliminated by T-cell-mediated killing." (PMID 38461299, 2024). "In an impressive study, CARM1 inactivation was found to activate innate immunity in melanoma resistant cell lines with high CARM1 expression, making them more sensitive to T cell immunity and immune checkpoint blockade." (PMID 35033016, 2022). "The combination of CARM1 inhibitors with CTLA4 or a PD-1 monoclonal antibody increased ICB efficacy in a melanoma mouse model as a result of the dual actions of CARM1 on T and tumor cells." (PMID 35493527, 2022). "In melanoma tumor cells, CARM1 ablation induced dsDNA breaks and cGAS-STING activation, together with the increased expression of several ISGs, including Irf7, Ifit1, Oasl1, and Tap1, and the enhancement of tumor cell susceptibility to cytotoxic T cells." (PMID 35493527, 2022). "In addition, there was no to low expression of CARM1 in brain tumors (a-b) and melanomas (c)." (PMID 20462455, 2010).
osteosarcoma (4 papers, 2023 to 2025). A usually aggressive malignant bone-forming mesenchymal neoplasm, predominantly affecting adolescents and young adults. "Recently, a study has shown that the expressions of ERK1/2, PARS40, and GSK3β are affected by CARM1, and the over‐expression of CARM1 promotes the proliferation of human osteosarcoma cells through the p‐GSK3β signaling pathway." (PMID 40611524, 2025). "A previous study showed that CARM1 promotes tumorigenesis via the pGSK3β/β-Catenin/cyclin D1 signaling pathway in osteosarcoma." (PMID 38476024, 2024). "Three PRMTs (i.e., PRMT1, PRMT4/CARM1 and PRMT5) have each been shown to control vitamin D3-dependent transcription in osteosarcoma cells via interactions with SRC-1/NCOA1, whereas PRMT5 binds to the SWI/SNF component BRG1/SMARCA4 in different cell types." (PMID 37593409, 2023). "PRMT1, PRMT4/CARM1, PRMT5 and PRMT7 are prevalent isoforms that are functionally expressed in myogenic cells and osteosarcoma cells." (PMID 37593409, 2023). "Our findings on the distinct functions of PRMT1, PRMT4/CARM1 and PRMT5 complement and extend previous studies that examined the contribution of PRMTs and their cognate epigenetic modifications in vitamin D3-dependent transcriptional regulation in rat osteosarcoma cells." (PMID 37593409, 2023).
ovarian tumors (4 papers, 2018 to 2025). "We showed that SCD1 inhibition suppresses the growth of CARM1-expressing ovarian tumor cells both in vitro and in vivo." (PMID 37377614, 2023). "To determine the effects of EZH2 inhibition in vivo on the growth of CARM1-expressing ovarian tumors, we utilized two xenograft models." (PMID 29434212, 2018). "We next sought to directly test whether SCD1 inhibition suppresses the proliferation of ovarian tumors in vivo in a CARM1 status–dependent manner." (PMID 37377614, 2023). "Inhibition of EZH2 activity using a clinically applicable small molecule inhibitor significantly suppresses the growth of CARM1-expressing, but not CARM1-deficient, ovarian tumors in two xenograft models and improves the survival of mice bearing CARM1-expressing ovarian tumors." (PMID 29434212, 2018). "Inhibition of EZH2 significantly suppresses the growth of CARM1-expressing, but not CARM1-nonexpressing, ovarian tumors." (PMID 37536629, 2023).
pancreatic ductal adenocarcinoma (4 papers, 2020 to 2025). An infiltrating adenocarcinoma that arises from the epithelial cells of the pancreas. "Additionally, they discovered that CARM1's activity is suppressed by reactive oxygen species (ROS), indicating that CARM1 could serve as a ROS sensor, regulating MDH1 activity and glutamine metabolism in pancreatic ductal adenocarcinoma (PDAC)." (PMID 39964832, 2025).
breast invasive carcinoma (3 papers, 2013 to 2021). "In this study, we demonstrated that CARM1 expression was increased in invasive breast cancer cells compared with adjacent benign epithelium." (PMID 23915145, 2013). "CARM1 expression in breast invasive carcinoma showed nuclear and/or cytoplasmic staining patterns, and each was scored separately." (PMID 23915145, 2013). "To determine the role of CARM1 expression in different subtypes of invasive breast carcinoma, we correlated the nuclear expression of CARM1 with tumor molecular subtypes." (PMID 23915145, 2013). "In addition, increased CARM1 expression was observed in both nucleus and cytoplasm in breast invasive carcinoma as compared with the matched benign tissues adjacent to the tumors." (PMID 26030442, 2015).
endometrial cancer (3 papers, 2012 to 2025). Primary or metastatic malignant neoplasm involving the endometrium (mucous membrane that lines the endometrial cavity). "They discovered that the selective inhibitor of CARM1, TP‐064, can inhibit the proliferation of endometrial cancer cells by inducing apoptosis." (PMID 39964832, 2025).